IL33 (interleukin 33)
Diseases named in the same sentence as IL33 in open-access papers (continued):
Sharing a sentence is not in itself a finding about the gene and the disease.
liver cancer (12 papers, 2015 to 2025). An epithelial or non-epithelial malignant neoplasm that arises from the liver. "High IL33 expression was associated with extended OS (HR = 0.41, p = 0.000041), indicating a positive correlation between IL33 expression and OS in liver cancer patients." (PMID 35011007, 2021). "In particular, a high IL33 level was associated with prolonged OS among liver cancer patients." (PMID 35011007, 2021). "Previous studies have linked IL-33 to cancer-prone chronic inflammation, prompting us to explore its role in HBV+DEN-associated liver cancer development." (PMID 40579434, 2025). "HBV-containing liver exposed to DEN upregulated interleukin-33 (IL-33), which was required for liver cancer development." (PMID 40579434, 2025). "To investigate the role of IL-33 in HBV+DEN-induced liver cancer, we subjected Il33 knockout (Il33KO), ST2 knockout (ST2KO), and Il33 transcription factor, Irf3, knockout (Irf3KO) mice to HBV+DEN liver carcinogenesis protocol." (PMID 40579434, 2025). "The study's findings accentuate the necessity for in‐depth research into IL‐33's specific roles and mechanisms within liver cancer, potentially uncovering new avenues for therapeutic intervention or enhancing the efficacy of existing treatments." (PMID 38923705, 2024). "Treatment with IL-33 to promote the recruitment of eosinophils can effectively inhibit the progression of liver cancer in mice." (PMID 39308686, 2024). "Repeated injection of IL-33 accelerated liver cancer growth in mice, as shown by the increased tumour size, weight, and Ki67 expression in the HCC tissue sections." (PMID 33308251, 2020). "Xie and colleagues confirmed that long-term stimulation of tobacco in liver cells was prone to induce the stemness properties of liver cancer cells by activating the IL-33/p38 signal axis." (PMID 32014008, 2020). "Investigating IL‐33 in the context of the liver cancer microenvironment might unveil innovative immunotherapeutic strategies or elucidate resistance mechanisms to current therapies, marking a promising frontier for exploration in cancer biology." (PMID 38923705, 2024). "Our results indicate that PPARγ is key in this interaction between ILC2s and cancer cells, by supporting ILC2s in their pro-tumoral functions, that might be conserved across different IL-33 dependent tumors, such as breast and liver cancer." (PMID 33953160, 2021). "We observed a higher IL-33 expression in liver cancer than in para-cancer tissues." (PMID 33308251, 2020). "We found that eosinophils activated by IL33 secreted MBP, indicating that the combination of KRG and NK cells suppressed metastatic liver cancer cells." (PMID 35011007, 2021). "Pitavastatin, an IL-33 inhibitor, suppresses HBV plus DEN-induced liver cancer." (PMID 40579434, 2025). "To determine the role of pitavastatin for liver cancer prevention in HBV-infected individuals, we treated WT mice with 2 mg/kg pitavastatin or PBS alone (carrier control) once a week during the HBV+DEN liver carcinogenesis protocol until harvest, which suppressed IL-33 levels." (PMID 40579434, 2025).
pancreatitis (12 papers, 2019 to 2025). Inflammation of the pancreas. "For example, nuclear IL-33 is a pro-pathogenic factor that contributes to disease progression in skin cancer, pancreatitis, pancreatitis-associated PDAC, and hepatocellular carcinoma." (PMID 38891990, 2024). "To further investigate the role of IL-33 in the progression of pancreatitis, we administered recombinant Il-33 intraperitoneally in an SAP mouse model." (PMID 41208897, 2025). "Collectively, these findings demonstrate that TBK1-IRF3 regulates IL-33 expression in chronic dermatitis and pancreatitis." (PMID 38816352, 2024). "IL-33 and IRF3 were highly expressed in the nucleus of epithelial cells in pancreatitis and pancreatitis-associated PDAC samples." (PMID 38816352, 2024). "In this Mini Review, we discuss the pathogenic roles played by IL-33 in the development of IBD and pancreatitis and consider the potential of this cytokine to be a new therapeutic target." (PMID 34759844, 2021). "Recent studies have provided evidence that IL-33 is an innate immune cytokine that bridges adaptive Th1 and Th2 responses associated with IBD and pancreatitis." (PMID 34759844, 2021). "In coxsackie B virus-induced pancreatitis, the administration of IL-33 enhances CD8+ T-cells and the IFN-γ-dependent antiviral immune response, resulting in a decrease in viral loads and the attenuation of pancreatitis." (PMID 31509992, 2019). "Both conditions may share pro-inflammatory cytokines, such as IL-33 and TNF-α, which intensify inflammation and predispose individuals to pancreatitis." (PMID 40417313, 2025). "To extend our findings to cancer-prone chronic inflammation in humans, we examined IL-33 and IRF3 expression in the epithelial cells across 15 matched samples of the normal pancreas, pancreatitis, and pancreatitis-associated pancreatic ductal adenocarcinoma (PDAC)." (PMID 38816352, 2024). "Il33 is expressed during pancreatitis by a small subset (4%) of TFF1/ANXA10+Kras-mutant Gastric module-expressing epithelial cells and is predicted to initiate signaling to Tregs and ILCs (Module T8) by binding with its cognate receptor Il1rl1 and co-receptor Il1rap." (PMID 37167403, 2023). "IL-33 is emerging as a pathogenic cytokine in IBD and pancreatitis." (PMID 34759844, 2021). "IL-33 and ST2 are highly expressed in chronic inflammatory diseases, including IBD, pancreatitis, hepatitis, and chronic obstructive pulmonary disease." (PMID 38816352, 2024). "IL-33, which promotes both Th1 and Th2 responses, has now emerged as a new proinflammatory cytokine promoting the development of IBD and pancreatitis." (PMID 34759844, 2021). "Although cellular sources of IL-33 are different in IBD and pancreatitis, IL-33 mediates tissue fibrosis in both disorders through induction of pro-fibrogenic factors such as IL-13." (PMID 34759844, 2021). "In this Mini Review, we summarize the key features of IL-33 in terms of its role in IBD and pancreatitis." (PMID 34759844, 2021). "In non-inflammatory pancreas, IL-33 is retained within the nuclei of acinar cells, whereas during pancreatitis, it is released extracellularly." (PMID 41208897, 2025). "In pancreas, lipoprotein disorder induces interleukin-33 (IL-33) expression and release in pancreatic stellate cell (PSC), which strongly induced pancreatic ILC2s to trigger a type 2 immune response accompanied by the activation of PSCs, eventually leading to fibrosis during pancreatitis." (PMID 36405734, 2022). "Thus, IL-33 is an attractive therapeutic target for IBD and pancreatitis." (PMID 34759844, 2021).
schistosomiasis (12 papers, 2016 to 2024). An infectious disease caused by parasitic trematodes of the genus Schistosoma that colonize human blood vessels and release eggs that can cause granulomatous reactions leading to acute (swimmer's itch or acute schistosomiasis syndrome) or chronic disease. "However, the role of IL-33/ST2 signalling in fibrosis caused by schistosomiasis remains poorly understood." (PMID 37373379, 2023). "Substantial evidence shows that the alarmin IL-33 was strongly produced by inflammation-damaged tissues in severe infectious diseases such as schistosomiasis and sepsis." (PMID 36371464, 2022). "ST2 is a unique IL-33 receptor, and appropriate inhibition of IL-33/ST2 reduces the immunopathology of schistosomes; however, knockdown of IL-33 or ST2 exacerbates schistosomiasis liver pathology." (PMID 36389166, 2022). "Our team has previously clarified that IL-33 contributed to schistosomiasis via inducing M2 macrophages polarization." (PMID 34674752, 2021). "IL-33 being a strong inducer of the Th2 immune response, the role of IL-33 in schistosomiasis has also been intensively studied." (PMID 31200771, 2019). "We further observed a significant reduction of plasma IL-33 levels in schistosomiasis only infected participants when compared to controls indicating a possible negative association of this cytokine with schistosomiasis infection (p = 0.003)." (PMID 31849991, 2019). "The role of IL-33 in schistosomiasis has also been intensively studied, but published reports have been inconsistent." (PMID 29554131, 2018). "In this study, using a well-studied murine model of human schistosomiasis, we show that Schistosoma infection down-regulates the miR-203-3p expression, and that IL-33, an inducer of type 2 immunity, is a direct target of miR-203-3p in hepatic stellate cells." (PMID 29554131, 2018). "IL-33 helps to maintain the Th2 immune microenvironment of the liver in mice infected with schistosomes, which plays a critical role in the hepatic immunopathology of schistosomiasis." (PMID 38105713, 2024). "In the current study, we provide data demonstrating that IL-33/ST2 signalling is an essential step for HSC activation during experimental schistosomiasis, and disruptions in this pathway result in inappropriate granuloma organisation with altered extracellular matrix composition." (PMID 37373379, 2023). "A recent work showed a negative association between plasma levels of IL-33, a type 2 immunity-related alarmin, and schistosomiasis and egg burden in school children from rural communities of Cameroon." (PMID 33777015, 2021). "Non-significant differences between age and gender distributions of egg-positive and egg-negative participants further reinforced the indication of a true negative association of schistosomiasis taken within a polyparasitic setting with plasma IL-33 concentration." (PMID 31849991, 2019). "The results showed that the levels of IL-33 and HMGB1 in the sera of advanced schistosomiasis patients were significantly higher than those in the sera of healthy individuals (F = 4.55, 212.09, P < 0.05)." (PMID 38105713, 2024). "However, the role of ILC2-activating cytokines IL-25, IL-33 and TSLP in schistosomiasis remains less understood." (PMID 33482904, 2021). "Our major finding is that of a significant propensity of schistosomiasis-infected hosts to have lower plasma IL-33 levels when compared to non-infected hosts." (PMID 31849991, 2019). "Moreover, all participants with schistosomiasis, co-infected or not, appeared to have a lower plasma concentration of IL-33 as demonstrated by the comparison of schistosomiasis negative and schistosomiasis positive participants irrespective of their status relating to other diseases screened." (PMID 31849991, 2019).
adenoma (11 papers, 2018 to 2025). A neoplasm arising from the epithelium. "General analysis revealed that no clinicopathological parameters were associated with tissue levels of either IL-33 or ST2 mRNAs in patients with adenomas." (PMID 30547011, 2018). "They found that IL-33 deficiency significantly reduced the formation of intestinal polyposis (adenoma) and mast cell accumulation in adenomatous polyps, suppressing the expression of mast cell-derived proteases and cytokines known to promote polyposis in ApcMin/+ mice." (PMID 30547011, 2018). "Indeed, we have found that the expression level of IL-33 mRNA is associated with dysplastic degree in adenomas." (PMID 30547011, 2018). "As the literature reports, adenoma/CRC cells express high levels of IL-33 mRNA, and our TO secrete higher levels of IL-33 compared to the healthy colon, supporting the strong validity of the TO model." (PMID 40372523, 2025). "According to these antecedents, IL-33 increase was observed mainly in adenomas (low grade adenocarcinoma and in tumors of stages I–III), decreasing later in stage IV." (PMID 31281317, 2019). "As illustrated in adenomas, we also found that both IL-33- and ST2-IRs are expressed in CRC cells, CD3 positive lymphocytes, SMA-alpha positive myofibroblasts, and CD34 positive microvessels within the CRC microenvironment." (PMID 30547011, 2018). "Immunohistochemical results revealed that IL-33-IR was highly expressed in adenoma cells, lymphocytes, stromal cells (myofibroblasts) and microvessels, indicating an autocrine/paracrine loop in those cells." (PMID 30547011, 2018). "Particularly, the density of IL-33-positive microvessels was significantly increased in adenoma stroma compared to normal controls." (PMID 30547011, 2018). "We and others have reported significant increase of IL-8 and VEGF expression in human adenoma and CRC specimens, which are similar to the expression profile of IL-33 in adenoma and CRC specimens." (PMID 30547011, 2018). "Results showed that IL-33 immunoreactivity (IR) is observed in diverse cells, including adenoma/CRC cells, CD3 positive lymphocytes, SMA-alpha positive myofibroblasts and CD34 positive endothelial cells of tumor-associated microvessels." (PMID 30547011, 2018). "We have examined the expression profile of IL-33 in human adenomas and found that expression levels of IL-33 mRNA are markedly increased in adenoma tissues." (PMID 30547011, 2018). "Thus, one of likely explanations is that ST2 is a potential functional mediator for IL-33 in stimulating Treg accumulation in the adenoma/CRC microenvironment." (PMID 32246094, 2020). "Interestingly, ST2 in the adenoma/CRC microenvironment is expressed in a very similar cellular pattern as IL-33." (PMID 30547011, 2018). "From the adenoma stage to the CRC stage, tumor-promoting relevant cytokines, such as IL-6, IL-8, IL-17A and IL-33, are significantly increased." (PMID 36466926, 2022). "Indeed, increased IL‐33/ST2 levels and increased IL‐33+ and ST2+ microvessel densities occur in the stroma of adenomas and CRCs, which suggests a contributing role of the IL‐33/ST2 pathway to CRC pathogenesis." (PMID 35791509, 2022). "We therefore concluded that increased densities of ST2-postive cells relate to Treg accumulation within the adenoma/CRC microenvironment, suggesting the IL-33/ST2 pathway as a potential contributor for immunosuppressive milieu formation that impact disease stage and prognosis in patients with CRC." (PMID 32246094, 2020). "We previously examined cell expressing IL-33 and ST2 in the human adenoma/CRC microenvironment." (PMID 30547011, 2018). "IL33/ST2 was first implicated in CRC in early studies that showed increased IL-33 expression in CRC patient tissues as compared to non-cancer adjacent tissues, correlating with transition from adenoma to carcinoma progression." (PMID 30205617, 2018).
adenoma (continued). "Because ST2 is the primary functional receptor for IL-33, which contributes to Treg expansion and function, our present results may imply that ST2 overexpression correlates to Treg accumulation in both the adenoma and CRC." (PMID 32246094, 2020). "In addition, IL-33, and total ST2 mRNA content were found elevated in tumor tissue of patients (adenomas > carcinomas) vs. normal tissue, and were related to increased invasion and metastasis in CRC tumor cells and xenograft murine models of a IL-33-overexpressing tumor cell line." (PMID 31281317, 2019).
allergic conjunctivitis (11 papers, 2012 to 2024). "This cytokine is known to be produced following IL33 signaling and has been implicated in disruption of the ocular surface barrier in allergic conjunctivitis." (PMID 35456761, 2022). "Because mast cells express IL-33R, IL-33 can participate in mast cell-mediated pathophysiological changes observed in allergic conjunctivitis via the induction of cytokines and chemokines released from mast cells." (PMID 38541674, 2024). "Their results suggest that IL-33, which contributes to the activation of Th2, mast cells, and eosinophil, can be a therapeutic target for treating individuals with allergic conjunctivitis." (PMID 38541674, 2024). "In a mouse model of allergic conjunctivitis, Matsuba-Kitamura demonstrated that conjunctival epithelial cells release IL-33." (PMID 38541674, 2024). "Epithelial cells of the ocular surface can participate in the pathogenesis of allergic conjunctivitis because of the expression of receptors for cytokines such as IL-9 and IL-33." (PMID 38541674, 2024). "IL-33 promotes type 2 immune responses in allergic conjunctivitis by mediating the release of Th2 cytokines by Th2 cells and mast cells." (PMID 38541674, 2024). "The role of IL-33 was also confirmed in the pathogenesis of allergic conjunctivitis using an experimental animal model of sensitization to ragweed pollen." (PMID 22349136, 2012). "IL-33 has a pathophysiological role in allergic conjunctivitis because it promotes the allergen-induced inflammatory process in the conjunctiva observed in individuals with allergic conjunctivitis." (PMID 38541674, 2024). "In addition to the corneal injury model, the role of IL-33 in ocular allergic diseases has been clarified in several studies using mouse models of allergic conjunctivitis." (PMID 35326502, 2022). "In experimental allergic conjunctivitis induced by short ragweed (SRW) pollen, typical allergic signs, stimulated IL-33/ST2 signaling and overproduced Th2 cytokine were observed in ocular surface, cervical lymph nodes and isolated CD4+ T cells of BALB/c mice." (PMID 27796360, 2016). "Recent studies showed that the IL-33 and its receptor ST2 play important roles in allergic conjunctivitis." (PMID 23585867, 2013).
chronic kidney disease (11 papers, 2017 to 2025). Impairment of the renal function secondary to chronic kidney damage persisting for three or more months. "Consequently, traditional risk factors and increased IL-33/ST2 levels in patients with chronic kidney disease are an indicator of increased inflammation, impaired endothelial functions, and cardiovascular events." (PMID 28614418, 2017). "Serum IL-33 levels were increased in chronic kidney disease patients and exhibited unfavorable survival." (PMID 36362231, 2022). "In this study, for the first time in literature, we aimed to investigate the levels of IL-33/ST2 in the different stages of chronic kidney disease and to determine their effects on vascular damage and cardiovascular outcomes." (PMID 28614418, 2017). "Furthermore, a previous study suggests an increased expression of IL33 in patients with chronic renal disease." (PMID 41235225, 2025). "Advancements in the study of IL-33/ST2 in chronic kidney disease (CKD)." (PMID 35046838, 2021). "Furthermore, IL-33 plays a role in chronic kidney disease development." (PMID 36362231, 2022). "There is increasing evidence that the IL-33/ST2 signaling pathway is involved in SLE, LN, and chronic kidney disease, as well as in the inflammatory pathogenesis of various kidney injury–related diseases." (PMID 36859530, 2023). "In a rat model of adenine-induced chronic kidney disease (CKD), adropin was found to reduce urine protein levels and 24-hour urine volume and downregulate inflammatory markers such as TIMP-1, IL-33, and MMP-2, suggesting a protective effect against renal damage and inflammation." (PMID 39766320, 2024). "This study is the first study to show that the IL-33/ST2 pathway is associated with increased cardiovascular events and poor outcomes in non-dialysis chronic kidney disease patients." (PMID 28614418, 2017).